RD3 (RD3 regulator of GUCY2D)
Description:
Plays a critical role in the regulation of enzymes involved in nucleotide cycle in photoreceptors. Inhibits the basal catalytic activity and the GCAP-stimulated activity of GUCY2D and GUCY2F, two retinal guanylyl cyclases involved in the production of cGMP in photoreceptors. Involved in the transport of GUCY2D and GUCY2F to their target sites in the photoreceptor outer segment. Up-regulates the activity of GUK1, a kinase that also plays an essential role for recycling GMP and indirectly, cGMP. Plays an important role for the survival of rods and cones in the retina (By similarity).
Synonyms: C1orf36; LCA12
Tractability: No criterion of Open Targets' tractability assessment is met for any kind of drug.
Gene: Protein-coding gene on chromosome 1 (211,476,522 to 211,492,484, reverse strand). Ensembl gene ENSG00000198570.
Subcellular location: Cell projection, cilium, photoreceptor outer segment; Photoreceptor inner segment; Endosome; Nucleus; Cytoplasm; Cytoplasm, perinuclear region
Gene Ontology:
Molecular function: protein binding
Biological process: negative regulation of guanylate cyclase activity; protein transport; retina development in camera-type eye; visual perception
Cellular component: cytoplasm; nucleus; perinuclear region of cytoplasm; endosome; photoreceptor inner segment; photoreceptor outer segment; cone photoreceptor outer segment; rod photoreceptor outer segment
Genetic constraint (gnomAD): Loss-of-function variants: 11 observed, 16.32 expected, observed/expected ratio (o/e) 0.67, 90% interval 0.42 to 1.12. The upper end of that interval is the gene's LOEUF score, 1.12, which puts it in group 4 of 6, group 1 being the genes least tolerant of losing a copy. Missense variants: 274 observed, 273.93 expected, observed/expected ratio (o/e) 1, 90% interval 0.9 to 1.11. Synonymous variants: 116 observed, 115.95 expected, observed/expected ratio (o/e) 1, 90% interval 0.86 to 1.17.
Gene-disease validity (ClinGen):
ClinGen rates the evidence that RD3 causes each of these diseases.
RD3-related retinopathy (autosomal recessive): Definitive. Any retinopathy caused by variants in the RD3 gene.
Homologues: Orthologues: chimpanzee RD3 (99% identical), macaque RD3 (96% identical), rat Rd3 (86% identical), mouse Rd3 (86% identical), pig RD3 (85% identical), dog RD3 (77% identical), guinea pig RD3 (66% identical), tropical clawed frog rd3 (61% identical), zebrafish rd3 (57% identical). Paralogues in human: RD3L (26% identical).
Diseases named in the same sentence as RD3 in open-access papers:
RD3 is named in the same sentence as 36 diseases in open-access papers, as found by Europe PMC text mining. Sharing a sentence is not in itself a finding about the gene and the disease. The quoted sentences say what the papers report.
retinal degeneration (15 papers, 2013 to 2025). Degeneration of the retina. "So far, several studies describe mutations in RD3 that cause LCA12, a severe form of retinal degeneration and cell dysfunction." (PMID 40234400, 2025). "Retinal Degeneration Protein 3 is involved in photoreceptor function and mutations in RD3 can lead to Leber congenital amaurosis, a disease that causes retinal degeneration and blindness." (PMID 41413636, 2025). "RD3 is a 23-kDa retinal protein that is essential for proper photoreceptor function, and the deletion of RD3 causes retinal degeneration and blindness in human patients that possess recessive Leber Congenital Amaurosis 12 (LCA)." (PMID 36157073, 2022). "Previous studies have shown that mice with a homozygous mutation in Rd3 exhibit retinal degeneration at three weeks after birth." (PMID 28487860, 2017). "For example, Rd3, which is associated with retinal degeneration, was identified as a missense substitution (A->T) with significant deleterious effects (p = 0.02)." (PMID 28487860, 2017). "In this study, we found that RD3, a retinal degeneration protein, is completely lost in patients with high-risk invasive disease, but not in patients with less invasive tumors." (PMID 26375249, 2015). "We proposed that aberrant activation of the retinal membrane guanylyl cyclase (RetGC) by its calcium-sensor proteins (guanylyl cyclase–activating protein [GCAP]) causes this retinal degeneration and that RD3 protects photoreceptors by preventing such activation." (PMID 34537244, 2021). "Although the mechanism by which RD3 loss mediates retinal degeneration has been extensively documented, the mechanism(s) involved in RD3 loss and loss-associated tumor progression are unknown." (PMID 29030614, 2017). "The RD3 gene was originally identified in the RD3 mouse strain exhibiting progressive retinal degeneration." (PMID 40234400, 2025). "Several models, including light-induced injury in BALB/c and C57BL/6 mice and monogenic/knockout models such as Pde6brd1, Prph2rd2, rd3-rd10 are a few common retinal degeneration models that are widely used for various experimental studies." (PMID 41326361, 2025). "In ocular studies, one retinal study found down-regulated CDS1 in retinal degeneration rd3 mouse by RNA microarray analysis." (PMID 33946922, 2021). "Our findings indicate that RD3 is involved in protecting photoreceptors from two different types of retinal degeneration—the recessive, such as LCA12, and the dominant, such as CORD6." (PMID 34537244, 2021). "Mutations in RD3 result in LCA12 in humans, a severe retinal degeneration in mice and rod–cone dysplasia type 2 (rcd2) in Collie dogs." (PMID 32260251, 2020). "Loss of RD3 function is connected to retinal degeneration in humans and leads to Leber congenital amaurosis type 12 (LCA12) indicating a crucial role of RD3 in photoreceptor physiology." (PMID 29515371, 2018). "The list of differentially expressed genes identified in the rd3 retina by this microarray study shares overwhelming similarity with that found in other microarray analyses examining the course of retinal degeneration." (PMID 23687432, 2013). "The microarray analysis of the rd3 retina revealed significant changes in the expression of an overlapping set of immune response genes found in several models of retinal degeneration and human retinal diseases." (PMID 23687432, 2013). "The RetGC1 trafficking in the absence of RD3 causes elevated cGMP levels in the inner segment, which turns on apoptosis that leads to retinal degeneration." (PMID 36157073, 2022). "We further suggested that insufficient inhibition of RetGC by RD3 could contribute to some dominant forms of retinal degeneration." (PMID 34537244, 2021). "However, beyond retinal localization and functions in retinal degeneration, the physiognomy and functions of RD3 are unknown." (PMID 31409909, 2019).
neuroblastoma (10 papers, 2014 to 2026). Neuroblastoma (NB) is the most common solid, extracranial childhood tumor. "Loss of RD3 expression correlates with the progression of the pathogenesis in neuroblastoma and a poor survival prognosis." (PMID 40234400, 2025). "Loss of RD3 function correlates with severe forms of retinal dystrophy and the development of aggressive neuroblastoma cancer." (PMID 40234400, 2025). "Our results resemble previous findings obtained from the tissue of neuroblastoma patients, in which the loss of RD3 is associated with tumor invasion, tumorsphere formation, and metastasis." (PMID 40234400, 2025). "The same authors further showed that RD3 loss in a mouse model correlates with aggressive neuroblastoma cancer." (PMID 36618828, 2022). "The same authors further showed that RD3 loss in a mouse model correlates with an aggressive neuroblastoma cancer." (PMID 29515371, 2018). "Recently, we identified significant loss of RD3 in high-risk neuroblastoma and the influential role of RD3 in tumor progression." (PMID 29030614, 2017). "RD3 loss is strongly correlated with advanced stages of neuroblastoma and with poor patient survival in multiple cohorts." (PMID 29030614, 2017). "Correlation analysis from multiple cohorts of neuroblastoma identified a strong association between RD3 loss and clinical outcomes, advanced disease, and poor OS and relapse-free survival." (PMID 26375249, 2015). "Using a clinically relevant animal model of high-risk human neuroblastoma, we found that RD3 transcriptional machinery is regulated in high-risk disease." (PMID 26375249, 2015). "To examine RD3 loss using our unique mouse model of aggressive neuroblastoma, first, we investigated differences in RD3 protein expression between the parental human SH-SY5Y cells and the clones of MSDACs." (PMID 26375249, 2015). "RD3-loss was intrinsically associated with reduced OS, abridged relapse-free survival, aggressive stage etc., in neuroblastoma patient cohorts." (PMID 26375249, 2015). "Human TMA data from the laboratory, clinical correlation data from manifold of neuroblastoma patient cohorts as well as the in vivo/ex vivo laboratory investigations unidirectionally dictates that RD3 loss mediates neuroblastoma progression." (PMID 26375249, 2015). "In this direction, in vitro/in vivo gene manipulation studies coupled with knock-in/knock-out double transgenic approaches are currently underway in our laboratory to pinpoint the role of RD3 loss in tumor invasion, metastasis, and neuroblastoma progression." (PMID 26375249, 2015). "To further substantiate RD3 loss in high-risk neuroblastoma in clinical settings, we utilized commercially available human neuroblastoma TMA." (PMID 26375249, 2015). "Evidently, gene manipulation studies demonstrated that loss of RD3 drives neuroblastoma cell migrations as well as heightened metastatic potential." (PMID 26375249, 2015). "This clinical data correlation, alongside our human TMA data correlations and results from in vivo experiments, directly demonstrates the definitive impact of RD3 loss in neuroblastoma progression." (PMID 26375249, 2015). "In every cohort of neuroblastoma patients, we found that RD3 loss significantly correlates with disease progression, with maximal loss in stage 4/4S." (PMID 26375249, 2015). "Gene manipulation approaches recognized that RD3 loss mediates tumor cell migration and metastatic potential in neuroblastoma cells." (PMID 26375249, 2015). "The data underscore the potential role of RD3 in the switch from favorable neuroblastoma to the high-risk aggressive disease." (PMID 26375249, 2015). "The results presented here show the significant loss of RD3 in high-risk aggressive metastatic neuroblastoma in vivo, ex vivo, and in clinical tumor specimens." (PMID 26375249, 2015). "In the animal model of human neuroblastoma, we found complete RD3 loss in a manifold of tumors from metastatic sites." (PMID 26375249, 2015).
neuroblastoma (continued). "Although these findings seem to contradict an earlier study concluding that inactivation of both RD3 alleles in LCA12 patients does not correlate with extraocular symptoms, a more recent study supports the direct involvement of RD3 loss in neuroblastoma development and progression." (PMID 40234400, 2025). "Moreover, RD3 plays a regulatory role in neuroblastoma progression and its loss is associated with aggressive neuroblastoma and poor clinical outcomes." (PMID 35884374, 2022). "In any event, the association of RD3 loss with the high-risk disease in multiple cohorts of neuroblastoma patients and RD3 protein influencing the regulation of tumor cell migration, invasion, and tumorosphere formation validates the causal role of RD3 protein in tumor progression." (PMID 29030614, 2017). "More importantly, RD3 loss is correlated with increased metastasis, and we demonstrated its novel ability to stabilize tumor evolution, underscoring RD3’s possible role in the switch from neuroblastoma with favorable prognosis to high-risk aggressive disease." (PMID 29030614, 2017). "RD3 loss is correlated with high-risk aggressive neuroblastoma." (PMID 26375249, 2015). "Interestingly, a study with a cohort of 64 neuroblastoma patients demonstrated a complete loss of RD3 as the tumor progressed." (PMID 26375249, 2015). "We then sought to define and typify the loss of RD3 in aggressive neuroblastoma." (PMID 26375249, 2015). "Additional studies with a cohort of 30 NB patients validated the complete loss of RD3 in high-risk aggressive metastatic stage 4 neuroblastoma." (PMID 26375249, 2015). "For example, previous work showed that RD3 is downregulated or lost in neuroblastoma cells that remained resistant to multi-modal clinical therapy." (PMID 36618828, 2022). "Earlier, we characterized the expression of RD3 in human neuroblastoma cells; the expression of RD3 is highly restricted in metastatic site-derived aggressive cells." (PMID 29030614, 2017). "The antibody explicitly detects RD3 protein, as evident from its immunoreactivity both in a panel of neuroblastoma cell lines and in a panel of human normal tissues." (PMID 29030614, 2017). "Conversely muting RD3 in neuroblastoma cells not only heightened invasion/migration but also dictated aggressive disease with metastasis." (PMID 26375249, 2015). "This study recognized the loss of Retinal Degeneration protein 3, RD3 in aggressive neuroblastoma, and identified its influence in better clinical outcomes and defined its novel metastasis suppressor function." (PMID 26375249, 2015). "In a cohort of 88 neuroblastoma patients, low RD3 expression was inversely correlated with overall patient survival." (PMID 26375249, 2015). "To that end, we investigated the localization and constitutive expression of RD3 protein in a collection of normal human tissues, and further compiled the RD3 transcriptional profile in normal tissues to enhance our understanding of RD3 in human tumors other than neuroblastoma." (PMID 29030614, 2017). "One could argue that understanding the basal levels of RD3 in human fetal tissues would be relevant to defining the role of RD3 in early childhood diseases, including neuroblastoma." (PMID 29030614, 2017). "In this study, we found that RD3 is significantly lost in human neuroblastoma tissues." (PMID 26375249, 2015). "To better underscore the significance of RD3 loss in high-risk neuroblastoma, first, we investigated the expression levels of RD3 in normal mouse and human tissues." (PMID 26375249, 2015). "To better characterize the loss of RD3 in high-risk neuroblastoma, first, we investigated the transcriptional regulation of RD3 in MSDACs with or without CSC marker positivity." (PMID 26375249, 2015).
neuroblastoma (continued). "While linc00467 had not been studied at all in the literature, we discovered that linc00467 suppressed the expression of its downstream protein-coding gene RD3, and induced neuroblastoma cell survival by reducing the expression of the tumour suppressor gene DKK1." (PMID 24586304, 2014). "Additionally, the authors suggest a metastasis suppressor function for RD3 in neuroblastoma." (PMID 29515371, 2018). "Immunoblot analysis was performed in several human neuroblastoma SH-SY5Y, SK-N-AS, SK-PNDW, and IMR-32 cells, as we have previously reported basal levels of RD3 expression in these cells." (PMID 29030614, 2017). "Third, although RD3 is strongly immunoreactive in some subsets of neuroblastomas and neuroblastoma cell lines, it is negative in the adrenal medulla, from which most adrenal neuroblastomas originate." (PMID 29030614, 2017). "While neuroblastoma is often RD3-positive, the adrenal medulla, where many neuroblastomas originate, is RD3-negative." (PMID 29030614, 2017). "For this, we examined the levels of RD3 transcription between non-metastatic and aggressive metastatic neuroblastoma cells in both in vivo and ex vivo settings utilizing the characterized mouse model of high-risk aggressive and metastatic neuroblastoma." (PMID 26375249, 2015).
Leber congenital amaurosis (8 papers, 2013 to 2025). Leber congenital amaurosis (LCA) is a retinal dystrophy defined by blindness and responses to electrophysiological stimulation (Ganzfeld electroretinogram (ERG)) below threshold, associated with severe visual impairment within the first year of life. "Retinal degeneration-3 protein (RD3) deficiency causes photoreceptor dysfunction and rapid degeneration in the rd3 mouse strain and in human Leber’s congenital amaurosis, a congenital retinal dystrophy that results in early vision loss." (PMID 33539922, 2021). "Mutations in the gene encoding RD3 resulting in unstable non-functional C-terminal truncated proteins are responsible for early onset photoreceptor degeneration in Leber Congenital Amaurosis 12 patients, the rd3 mice, and the rcd2 collies." (PMID 24904271, 2014). "Our proteomic data showed significant changes in the levels of proteins for retinitis pigmentosa (RPE65, RP2, MERTK, and RBP3), X-linked retinoschisis (RS1), CRB1-retinal dystrophy (CRB1), Usher syndrome (PCDH15), and Leber congenital amaurosis (RD3 and KCNJ13)." (PMID 36139394, 2022). "RD3 deficiency reduces RetGC content in the photoreceptor outer segment and suppresses retinal photoresponses, making rods and cones dysfunctional from birth in recessive human Leber’s congenital amaurosis-12 (LCA12) and rd3 mouse strain." (PMID 33539922, 2021).
Leber congenital amaurosis type 12 (7 papers, 2014 to 2025). "Genetic deficiencies and mutations of RD3 cause early-onset photoreceptor degeneration in patients with Leber congenital amaurosis type 12 (LCA12)." (PMID 40234400, 2025). "RD3 was first identified as the product of a gene disrupted by mutations causing recessive degenerative retinal blindness in humans (Leber's congenital amaurosis type 12 [LCA12]) and in rd3 mouse strain (Rd3−/−)." (PMID 34537244, 2021). "Retinal degeneration protein 3 (RD3) is crucial for photoreceptor cell survival and linked to Leber Congenital Amaurosis type 12 (LCA12), a hereditary retinal disease in humans." (PMID 29515371, 2018). "In this study, we have confirmed that knocking-down linc00467 up-regulates the expression of its neighbouring protein-coding gene RD3, which encodes a retinal protein responsible for the retinal degeneration disorder Leber congenital amaurosis type 12." (PMID 24586304, 2014).
Blindness (4 papers, 2014 to 2023). Blindness is the condition of lacking visual perception defined as a profound reduction in visual perception. "Mutations in RetGC1, GCAP1 and RD3 that disable the Ca2+-dependent cyclase regulation are genetically linked to retinal degenerative diseases and inherited forms of blindness." (PMID 36157073, 2022). "Mutations in RetGC1, GCAP1 or RD3 that disable the Ca2+-dependent regulation of cyclase activity are genetically linked to rod/cone dystrophies and other inherited forms of blindness." (PMID 36157073, 2022). "In addition, the deficiency of RD3 causes severe photoreceptor degeneration and blindness in recessive LCA, as well as in the rd3 mouse strain." (PMID 37446378, 2023). "To test the hypothesis that the GCAP proteins contribute to the physiopathology of blindness associated to the lack of functional RD3, we bred rd3 mice to GCAP1/GCAP2 double knockout mice (GCAPs−/− mice), to assess whether the retinal degeneration was delayed." (PMID 31980596, 2020).
congenital blindness (4 papers, 2020 to 2022). "Retinal degeneration-3 protein (RD3) deficiency in photoreceptors leads to recessive congenital blindness." (PMID 34537244, 2021). "We tested how the mutations causing recessive congenital stationary night blindness (CSNB), recessive Leber's congenital amaurosis (LCA1), and dominant cone-rod dystrophy-6 (CORD6) affected RetGC1 activity and regulation by RetGC-activating proteins (GCAPs) and retinal degeneration-3 protein (RD3)." (PMID 33109612, 2020). "Furthermore, a previous study on the gene expression pattern in the rd3 mouse, an animal model of congenital blindness with low or no rd3 expression, reported that more than 1,000 genes are differentially regulated." (PMID 36618828, 2022).